MT-ND3 (mitochondrially encoded NADH:ubiquinone oxidoreductase core subunit 3)
Description:
Core subunit of the mitochondrial membrane respiratory chain NADH dehydrogenase (Complex I) which catalyzes electron transfer from NADH through the respiratory chain, using ubiquinone as an electron acceptor. Essential for the catalytic activity of complex I.
Synonyms: ND3; NAD3; formerly MTND3
Tractability: Small molecule: an approved drug acts on it; a structure with a bound ligand is known. Antibody: UniProt predicts a signal peptide or a membrane-spanning region.
Gene: Protein-coding gene on chromosome MT (10,059 to 10,404, forward strand). Ensembl gene ENSG00000198840.
Subcellular location: Mitochondrion inner membrane
Subcellular location (Human Protein Atlas): Cytosol
Pathways (Reactome):
Metabolism: Complex I biogenesis; Respiratory electron transport
Metabolism of proteins: Mitochondrial translation termination
Gene Ontology:
Molecular function: NADH dehydrogenase (ubiquinone) activity; protein binding
Biological process: mitochondrial electron transport, NADH to ubiquinone; aerobic respiration; proton motive force-driven mitochondrial ATP synthesis; cellular response to glucocorticoid stimulus; proton transmembrane transport; response to hormone; response to light intensity; response to oxidative stress
Cellular component: mitochondrial inner membrane; mitochondrion; respiratory chain complex I
Gene-disease validity (ClinGen):
ClinGen rates the evidence that MT-ND3 causes each of these diseases.
Leigh syndrome (mitochondrial): Definitive. A progressive neurological disease defined by specific neuropathological features associating brainstem and basal ganglia lesions.
mitochondrial disease (mitochondrial): Definitive.
Homologues: Orthologues: chimpanzee MT-ND3 (95% identical), macaque ND3 (77% identical), rabbit MT-ND3 (72% identical), pig ND3 (71% identical), guinea pig MT-ND3 (68% identical), rat Mt-nd3 (68% identical), mouse mt-Nd3 (66% identical), zebrafish mt-nd3 (56% identical), tropical clawed frog ND3 (53% identical), Drosophila melanogaster mt:ND3 (37% identical).
Diseases named in the same sentence as MT-ND3 in open-access papers:
MT-ND3 is named in the same sentence as 78 diseases in open-access papers, as found by Europe PMC text mining. Sharing a sentence is not in itself a finding about the gene and the disease. The quoted sentences say what the papers report.
breast carcinoma (15 papers, 2009 to 2026). "Five mitochondrial genes (MT-ND4, MT-ND1, MT-ND3, MT-ND6, and MT-ND2), which were identified as key genes of the complex I biogenesis pathway by Pathformer, were also reported to be associated with breast cancer prognosis." (PMID 38741230, 2024). "In a study conducted on a Polish population, a total of 28 changes were detected in MT-ND1, MT-ND2, MT-ND3 and MT-ND6 in breast cancer cells, which were described in databases as polymorphisms." (PMID 37189801, 2023). "Role of A10398G in the MT-ND3 gene in relation to breast cancer had been inconsistent." (PMID 36758048, 2023).
Leigh syndrome (13 papers, 2014 to 2025). "For example, the MT-ND3 S45P variant, which is associated with the Leigh syndrome (MIM #256000), is predicted by the previous energetic analysis to be stabilized by three co-occurring other residues located in position 126 of the interacting MT-ND3 protein." (PMID 33300029, 2021). "Among them, several studies have found that Leigh syndrome with MT-ND3 mutation (hereafter referred as Leigh syndrome with MT-ND3 mutation) is strongly associated with epilepsy." (PMID 34956047, 2021). "The seven patients with Leigh syndrome with MT-ND3 mutation were divided into the m.10191T>C and the m.10158T>C groups, according to the respective nucleotide change." (PMID 34956047, 2021). "Several studies have suggested that Leigh syndrome with MT-ND3 mutation is strongly associated with epilepsy." (PMID 34956047, 2021). "In this study, the six patients with the m.10191T>C mutation were associated with epilepsy, suggesting that this mutation is important in Leigh syndrome with MT-ND3 mutation." (PMID 34956047, 2021). "This study focused on the epilepsy-related characteristics of Leigh syndrome with MT-ND3 mutation identified in a single tertiary hospital in South Korea." (PMID 34956047, 2021). "Among the seven patients with Leigh syndrome with MT-ND3 mutation, the male-to-female ratio was 2:5." (PMID 34956047, 2021). "In conclusion, the results of this study indicate a strong association between epilepsy and Leigh syndrome with MT-ND3 mutation, particularly the m.10191T>C mutation." (PMID 34956047, 2021). "This knowledge may assist neurologists with the development of treatment plans and prognosis predictions for the patients with Leigh syndrome with the MT-ND3 mutation." (PMID 34956047, 2021). "Understanding the characteristics of Leigh syndrome with MT-ND3 mutation may assist in predicting disease progression and improving patient survival through timely treatment." (PMID 34956047, 2021). "The prevalence of epilepsy was high in Leigh syndrome with MT-ND3 mutation (n = 6)." (PMID 34956047, 2021). "General characteristics of Leigh syndrome with MT-ND3 mutation (Total N = 7)." (PMID 34956047, 2021). "The current status of deterioration was also measured and progressive deterioration was observed in four of the seven patients of Leigh syndrome with MT-ND3 mutation and the remaining three patients had a static status and no longer experienced progressive deterioration." (PMID 34956047, 2021). "Therefore, in this study, we focused on the epilepsy-related characteristics of the cases of Leigh syndrome with MT-ND3 mutation identified in a single tertiary hospital in Korea." (PMID 34956047, 2021). "Epilepsy characteristics of Leigh syndrome with MT-ND3 mutation (Total N = 7)." (PMID 34956047, 2021). "The third patient had MT-ND3-associated Leigh syndrome and an unknown perinatal history." (PMID 24731534, 2014). "The second patient, diagnosed with Leigh syndrome and NARP (neurogenic muscle weakness, ataxia, and retinitis pigmentosa), had a 91.1% heteroplasmic MT-ND3, m.10197G > A p.Ala47 Thr mutation." (PMID 40336053, 2025).
MELAS (9 papers, 2020 to 2025). "The second cluster consisted of all patients harboring isolated complex IV deficiency, three patients with isolated complex I deficiency (TIMMDC1 and mt-ND3), one patient with complex V deficiency, one MELAS patient, and one patient with DNA polymerase subunit gamma (POLG) deficiency." (PMID 39801833, 2025). "All four patients with mutations in MT-ND1 or MT-ND3 had LS, whereas patients with MT-ND5 mutations presented equally often with LS or MELAS." (PMID 31996177, 2020). "Most cases of the 10191T>C MT-ND3 mutation have a clinical presentation of LS, MELAS/LS, or nonspecific encephalopathy." (PMID 34025555, 2021). "Among MELAS patients, 2/6 (33.3%) harbored the m.3243A > G/MT‐TL1 mutation and 4/6 (66.7%) harbored other rare mtDNA mutations: two had the 10197G > A and 10191T > C MT‐ND3 mutation, one had the 3271T > C/MT‐TL1 mutation, and one had the 6597C > A/MT‐CO1 mutation." (PMID 33951347, 2021).
Parkinson disease (6 papers, 2010 to 2026). A progressive degenerative disorder of the central nervous system characterized by loss of dopamine producing neurons in the substantia nigra and the presence of Lewy bodies in the substantia nigra and locus coeruleus. "KEGG Pathways showed that the proteins were involved in prion disease (ND5, MT-ND3, etc.; p-value = 1.45E-06), Parkinson’s disease (MT-ND3, etc.; p-value = 1.45E-06), etc." (PMID 36891514, 2023).
Leber hereditary optic neuropathy (4 papers, 2021 to 2025). Leber's hereditary optic neuropathy (LHON) is a mitochondrial neurodegenerative disease affecting the optic nerve and often characterized by sudden vision loss in young adult carriers. "A 35-year-old female with severe spastic paraplegia and optic atrophy, included among AR cases as one deceased sister was similarly affected, carried a pathogenic variant affecting a conserved position in the mtDNA-encoded gene MT-ND3 gene." (PMID 33669240, 2021).
epilepsy (3 papers, 2019 to 2024). A brain disorder characterized by episodes of abnormally increased neuronal discharge resulting in transient episodes of sensory or motor neurological dysfunction, or psychic dysfunction. "Some studies have found that m.10191T>C, a major nucleotide change in MT-ND3 gene, is strongly related to epilepsy." (PMID 34956047, 2021).
leprosy (2 papers, 2013 to 2023). Leprosy is a chronic infectious disease affecting primarily the skin and peripheral nervous system. "Other mRNAs were also less expressed in leprosy patients when compared to non-leprous samples, such as Bad, IL10, IL12 as well as several mitochondrial genes (mtCOX2, mtND1, mtND3 mtND5 mtATP6, and mtCYB)." (PMID 23798993, 2013).
pancreatic cancers (2 papers, 2021 to 2023). "Major mitochondrial genes including MT-ND3, MT-CO1, IDH2, and TFAM are being reported in various pancreatic cancers, including PDAC (based on cBioportal data), but their actual roles in PDAC progression need further validation." (PMID 36831413, 2023).
breast tumours (1 paper, 2014). "The purpose of this study was to analyze mutations in MT-ND1, MT-ND2, MT-ND3 and MT-ND6 genes and their effect on the biochemical properties, structure and functioning of proteins in patients with breast tumours." (PMID 24414975, 2014).
invasive ductal carcinoma (1 paper, 2023). "Interestingly several variants were observed exclusively in patients with invasive ductal carcinoma (NST/NOS) and these included a missense variant each in MT-ND1 (A3434G), MT-ND2 (G4491A), MT-TD (T7581C), MT-CO2 (G7859A), MT-ND3 (G10143A)." (PMID 36758048, 2023).
male infertility (1 paper, 2025). The inability of the male to effect fertilization of an ovum after a specified period of unprotected intercourse. "This study analyzed the frequency of single-nucleotide polymorphisms (SNPs) in mitochondrial genes (MT-ND4, MT-ND4L, and MT-ND3) and their potential correlation with primary and secondary male infertility." (PMID 40843731, 2025). "This study explored the role of single-nucleotide polymorphisms (SNPs) in mitochondrial genes (MT-ND3, MT-ND4L, and MT-ND4) in primary and secondary male infertility." (PMID 40843731, 2025). "The current study aimed to investigate the role of single-nucleotide polymorphisms (SNPs) in the MTND3, MTND4L, and MTND4 genes related to both primary and secondary male infertility by comparing their genotypic profiles using Sanger sequencing." (PMID 40843731, 2025).
mitochondrial complex deficiency (1 paper, 2025). "Mutations in genes such as TTC19, SURF1, and PET100, which are associated with mitochondrial complex deficiency, as well as mutations in MT-ND3 linked to mitochondrial DNA-associated Leigh syndrome and NARP, were identified." (PMID 40336053, 2025).
neuropathy (1 paper, 2024). A disorder affecting the nervous system that manifests with pain, tingling, numbness, and/or muscle weakness. "The mt-Nd3 and mt-Nd4l genes predict the activation of NADH dehydrogenase (ubiquinone) activity in mitochondria, which is associated with mitochondrial function and regulation of neuropathy." (PMID 39796522, 2024).
cancer (14 papers, 2010 to 2025). A tumor composed of atypical neoplastic, often pleomorphic cells that invade other tissues. "Of these 32, several genes (mt-Nd3, mt-Nd4l) involved in mitochondrial metabolism have emerged, as well as other genes such as Epcam and Gprc5c involved in cancer stemness and dormancy of HSCs, respectively, and Cdcp1 that is expressed on leukemic blasts." (PMID 34550965, 2021). "The m.10398G > A is a non-synonymous SNP in the MT-ND3 gene, and it has been speculated that this alternation in Complex I would result in higher ROS production and increased apoptosis of normal cells, thereby allowing proliferation of cancer cells." (PMID 35743133, 2022). "Also among the upregulated genes were mitochondrial protein coding genes (MT-ND3, MT-ND4L, MT-ND4, MT-ND2, MT-CYB, MT-ND1, MT-CO1 etc), which may be as a result of the elevated metabolism characteristic of cancer cells to sustain their survival." (PMID 29132323, 2017).
tumor (9 papers, 2017 to 2025). "Interestingly, in patient #2, majority of the tumor epithelial cells in the primary tumor had a heteroplasmic mutation in MT-ND3(chrM:10192), but at liver metastasis (LM) region, almost all cells had homoplasmic mutations at MT-ND3(chrM:10192)." (PMID 35974387, 2022). "In addition, tumor cells of PTR1 and other regions had different mutations at MT-ND6(chrM:14504 - PTR1) and MT-ND3(chrM:10396 - PTR2-PTR3, LyM, LM), respectively." (PMID 35974387, 2022).
movement disorder (1 paper, 2021). Neurological conditions resulting in abnormal voluntary or involuntary movement, which may impact the speed, fluency, quality and ease of movement. "A predominant gene or a predominant mutation did not appear, reflecting the heterogeneous movement disorder manifestations; however, it appeared that children with hyperkinetic onset had a quite high occurrence of mutations in the MT-ND3 gene." (PMID 34065803, 2021).
MT-ND3 also shares sentences with these, for which no sentence is quoted: prostate carcinoma (4 papers); COVID-19 (3); infection (3); MELAS syndrome (3); Stroke (3); Adult onset (2); Encephalopathy (2); gastric cancer (2); hepatocellular carcinoma (2); ischemia (2); lactic acidosis (2); melanoma (2); mitochondrial disease (2); type 2 diabetes mellitus (2); Alpers syndrome (1); angina (1); asthma (1); Ataxia (1); bipolar disorder (1); bone carcinoma (1); carcinosarcoma (1); cardiomyopathy (1); cardiovascular diseases (1); colon cancers (1); colorectal cancer (1); coronary artery disease (1); diabetes (1); Dystonia (1); end-stage renal disease (1); endometrial cancer (1).
A further 32 diseases each share a sentence with MT-ND3 in 1 paper.